ENSG00000269307 (novel transcript)
Gene: Protein-coding gene on chromosome 19 (17,267,418 to 17,282,966, forward strand). Ensembl gene ENSG00000269307.
Genetic constraint (gnomAD): Missense variants: 142 observed, 139.37 expected, observed/expected ratio (o/e) 1.02, 90% interval 0.89 to 1.17. Synonymous variants: 54 observed, 49.81 expected, observed/expected ratio (o/e) 1.08, 90% interval 0.87 to 1.36.